TUBB8 (tubulin beta 8 class VIII)
Description:
Tubulin is the major constituent of microtubules, a cylinder consisting of laterally associated linear protofilaments composed of alpha- and beta-tubulin heterodimers. Microtubules grow by the addition of GTP-tubulin dimers to the microtubule end, where a stabilizing cap forms. Below the cap, tubulin dimers are in GDP-bound state, owing to GTPase activity of alpha-tubulin. TUBB8 has a key role in meiotic spindle assembly and oocyte maturation.
Synonyms: bA631M21.2; OOMD; OOMD2; OZEMA2
Tractability: Small molecule: an approved drug acts on it; a high-quality ligand is known; it belongs to a druggable protein family. PROTAC: ubiquitination databases record sites on it; a small molecule that binds it is known. Other modalities: an approved drug acts on it.
Target class: Structural protein
Gene: Protein-coding gene on chromosome 10 (46,888 to 74,163, reverse strand). Ensembl gene ENSG00000261456.
Subcellular location: Cytoplasm, cytoskeleton; Cytoplasm, cytoskeleton, spindle
Subcellular location (Human Protein Atlas): Microtubules; Basal body; Cytokinetic bridge; End piece; Flagellar centriole; Mitotic spindle; Primary cilium; Primary cilium tip; Principal piece
Pathways (Reactome):
Cell Cycle: EML4 and NUDC in mitotic spindle formation; Mitotic Prometaphase; Recruitment of NuMA to mitotic centrosomes; Resolution of Sister Chromatid Cohesion; Sealing of the nuclear envelope (NE) by ESCRT-III; Separation of Sister Chromatids; The role of GTSE1 in G2/M progression after G2 checkpoint
Vesicle-mediated transport: COPI-dependent Golgi-to-ER retrograde traffic; COPI-independent Golgi-to-ER retrograde traffic; COPI-mediated anterograde transport; Gap junction assembly; Microtubule-dependent trafficking of connexons from Golgi to the plasma membrane; Translocation of SLC2A4 (GLUT4) to the plasma membrane
Immune System: MHC class II antigen presentation; PKR-mediated signaling
Neuronal System: Activation of AMPK downstream of NMDARs; Assembly and cell surface presentation of NMDA receptors
Signal Transduction: RHO GTPases Activate Formins; RHO GTPases activate IQGAPs
Autophagy: Aggrephagy
Cellular responses to stimuli: HSP90 chaperone cycle for steroid hormone receptors (SHR) in the presence of ligand
Developmental Biology: Recycling pathway of L1
Disease: HCMV Early Events
Hemostasis: Kinesins
Metabolism of proteins: Carboxyterminal post-translational modifications of tubulin
Organelle biogenesis and maintenance: Cargo trafficking to the periciliary membrane
Gene Ontology:
Molecular function: protein binding; GTP binding; structural constituent of cytoskeleton; GTPase activity
Biological process: oocyte maturation; spindle assembly involved in female meiosis; mitotic cell cycle; microtubule-based process
Cellular component: ciliary tip; cilium; extracellular exosome; intercellular bridge; meiotic spindle; microtubule cytoskeleton; mitotic spindle; sperm end piece; sperm principal piece; cytoskeleton; microtubule; spindle
Genetic constraint (gnomAD): Loss-of-function variants: 22 observed, 24.42 expected, observed/expected ratio (o/e) 0.9, 90% interval 0.64 to 1.29. The synonymous counts are far from expectation, so gnomAD's model fits this gene poorly and the ratio says little. Missense variants: 249 observed, 451.34 expected, observed/expected ratio (o/e) 0.55, 90% interval 0.5 to 0.61. Synonymous variants: 228 observed, 174.59 expected, observed/expected ratio (o/e) 1.31, 90% interval 1.17 to 1.46.
Homologues: Paralogues in human: TUBB8B (96% identical), TUBB4B (91% identical), TUBB4A (90% identical), TUBB2B (89% identical), TUBB (89% identical), TUBB2A (89% identical), TUBB3 (87% identical), TUBB6 (86% identical), TUBB1 (77% identical), TUBA1B (43% identical), TUBA1A (43% identical), TUBA1C (42% identical), and 11 more.
Diseases named in the same sentence as TUBB8 in open-access papers:
TUBB8 is named in the same sentence as 7 diseases in open-access papers, as found by Europe PMC text mining. Sharing a sentence is not in itself a finding about the gene and the disease. The quoted sentences say what the papers report.
infertile (12 papers, 2020 to 2025). "The personalization of infertility care significantly improves with the incorporation of TUBB8, KIF11, and CKAP5 into the diagnostic framework of assisted reproduction." (PMID 40650169, 2025). "In the study by Yao, Z., a total of five heterozygous/homozygous mutations in TUBB8 were found in eleven infertile women (p.A313V, p.C239W, p.R251Q, p.P358L, and p.G96R)." (PMID 39684710, 2024). "TUBB8 variants have a high proportion of infertile females, and males who carried TUBB8 variants are fertile." (PMID 36197634, 2023). "In family 1, a novel heterozygous missense mutation in TUBB8, c.538G > A (p.V180M), was found in the proband (II-2), her elderly fertile brother (II-1), and her younger sister (II-4) who also suffered from infertility." (PMID 36197634, 2023). "In light of the unfavorable reproductive outcomes in females harboring pathogenic TUBB8 variants, genetic screen of TUBB8 is of great importance to females diagnosed with primary infertility, and genetic counselling should be conducted cautiously." (PMID 38007525, 2023). "As of today, some in-vivo studies have been exploring the treatment for infertile patients with TUBB8 mutations." (PMID 35354490, 2022). "The prevalence of TUBB8 mutations in 11 infertile women with oocyte maturation defects was established in this study by genetic analysis." (PMID 35354490, 2022). "In the present study, we focused on continuously expanding the sample size to detect the mutation frequency of the TUBB8 gene during oocyte maturation arrest in infertile women, emphasizing the prevalence of new TUBB8 mutations during that process." (PMID 35354490, 2022). "A total of five TUBB8 heterozygous/homozygous mutations were found in eleven infertile females (p.A313V, p.C239W, p.R251Q, p.P358L, and p.G96R)." (PMID 35354490, 2022). "Interestingly, Tubb5 and Tubb4a have high homology to primate-specific Tubb8, and Tubb8 mutations in women are associated with meiosis I arrest in oocytes and infertility." (PMID 39480006, 2024). "However, women with infertility caused by TUBB8 variants were able to conceive through egg donation." (PMID 36197634, 2023). "This study aims to identify novel TUBB8 variants and relevant phenotypes in more infertile females." (PMID 38007525, 2023). "Mutations in TUBB8 have been identified in infertile women with oocyte maturation arrest." (PMID 33152014, 2020). "It is worth noting that a recent study has demonstrated that the ectopic expression of TUBB8 resulted in mouse oocyte aneuploidy, and female mice ectopically expressing human TUBB8 were completely infertile." (PMID 39834092, 2025). "This thorough study presents new insights into the molecular mechanisms of infertility in women with unresolved oocyte arrest syndromes, highlighting the essential roles of TUBB8, KIF11, and CKAP5 in oocyte maturation and early embryonic development." (PMID 40650169, 2025). "TUBB8 and BUB3 were already associated with infertility due to oocyte meiotic arrest and mosaic variegated aneuploidy syndrome, respectively." (PMID 36999055, 2023). "TUBB8 should be considered a genetic marker for genetic counseling in infertile women with oocyte or embryonic defects to improve the efficiency of genetic diagnosis." (PMID 35354490, 2022). "Several studies have been published describing infertility cases with oocyte maturation arrest; however, heterozygous TUBB8 mutations were not discovered during our work on the genetic basis of oocyte arrest until 2016." (PMID 35354490, 2022). "The elucidation of molecular pathways involving TUBB8, KIF11, and CKAP5 has transformative potential in the diagnosis and treatment of infertility, particularly in cases with unresolved oocyte maturation arrest and early embryonic developmental failure." (PMID 40650169, 2025). "Other major DEPs, including RNASEH2C, TAPBPL, TUBB8, NFRKB, MASTL, and MYLK, have never been reported to be associated with infertility, metabolic disorders, or hormone imbalances." (PMID 34016141, 2021).
female infertility (9 papers, 2017 to 2025). Diminished or absent ability of a female to achieve conception. "In summary, our study characterises a comprehensive mechanism for TUBB8 missense variants responsible for human oocyte maturation arrest at metaphase I, thus opening new avenues for clinical interventions in treating female infertility." (PMID 39834092, 2025). "Altogether, a deeper and more comprehensive understanding of TUBB8 missense variants causing oocyte maturation arrest and female infertility is urgently needed." (PMID 39834092, 2025). "Our study provided a tremendous advance in understanding and treating female infertility associated with TUBB8 missense variants." (PMID 39834092, 2025). "Our study provides a comprehensive mechanism elucidating how TUBB8 missense variants cause oocyte maturation arrest and offers new therapeutic avenues for treating female infertility in the clinic." (PMID 39834092, 2025). "Female infertility resulting from TUBB8 missense variants encompasses a broad range of pathogenic missense variants associated with oocyte meiotic arrest." (PMID 39834092, 2025). "Recent studies have expanded the known TUBB8 mutational spectrum associated with female infertility, screening hundreds of pathogenic variants." (PMID 39834092, 2025). "TUBB8-deficiency primary female infertility had a poor prognosis in assisted reproductive treatment." (PMID 36197634, 2023). "The missense variants of TUBB8 usually cause female infertility in a heterozygous pattern via dominant-negative effects, while loss-of-function variants are usually pathogenic when present in a compound heterozygous or homozygous pattern." (PMID 38007525, 2023). "This study provides a possible means of treating female infertility caused by TUBB8 variants and it seems to be a very promising direction for subsequent research." (PMID 38007525, 2023). "The genotype-phenotype relationships between TUBB8 variants and female infertility are difficult to clearly define due to the complex inheritance patterns and the highly heterogeneous phenotypes." (PMID 38007525, 2023). "Until recently, a genetic study reported that TUBB8 mutations have dominant-negative effects that disrupt microtubule behavior and oocyte meiotic spindle assembly and maturation, causing female infertility." (PMID 29796058, 2018). "Screening for TUBB8 mutation demonstrated the diagnostic utility of female infertility." (PMID 36197634, 2023). "However, the pathogenic genes of female infertility were hidden until the first gene TUBB8 was reported to cause oocyte maturation arrest." (PMID 35620457, 2022). "The mutations of TUBB8, a microtubule related gene, have recently been identified as the genetic cause of human oocyte maturation arrest which occurs frequently in the clinical in vitro fertilization, leading to female infertility." (PMID 27906670, 2017). "In this study, we designed a target-sequencing panel with 22 female infertility-related genes, namely, TUBB8, PATL2, WEE2, and PANX1 and sequenced 68 primary infertility (PI) and recurrent pregnancy loss (RPL) patients." (PMID 35620457, 2022). "Therefore, we propose that a special fraction of TUBB8 missense variants, which do not impair α/β‐tubulin dimer production, disrupt oocyte maturation arrest and result in female infertility." (PMID 39834092, 2025). "Some TUBB8 variants of dominant inheritance have significant negative effects, which interfere with microtubule behavior and meiotic spindle assembly of oocytes, leading to arrest of oocyte maturation and female infertility." (PMID 32316999, 2020).
E. coli infection (1 paper, 2019). "Enrichment analysis using the KEGG database revealed the significant participation of detected proteins in pathogenic E. coli infection (ACTG1, TUBA1C, TUBA4A, TUBB, TUBB8, and YWHAZ), which may indicate microbiota changes associated with being in space." (PMID 31547269, 2019).
cancer (2 papers, 2018 to 2023). A tumor composed of atypical neoplastic, often pleomorphic cells that invade other tissues. "Similarly, other additional tubulin isotypes TUBB2B, TUBB8, and TUBA1C, which I observed in first level of our selection steps, were previously reported to involve in nucleation of MT, cancer progression, oocyte maturation, and neuronal abnormalities." (PMID 37466845, 2023).
TUBB8 also shares sentences with these, for which no sentence is quoted: genetic diseases (1 paper); metabolic disorders (1); tubulinopathies (1).